IGLC5 (immunoglobulin lambda constant 5 (pseudogene))
Synonyms: IGLC
Gene: Gene (Ensembl biotype IG_C_pseudogene) on chromosome 22 (22,915,635 to 22,915,927, forward strand). Ensembl gene ENSG00000254030.
Diseases named in the same sentence as IGLC5 in open-access papers:
IGLC5 is named in the same sentence as 1 disease in open-access papers, as found by Europe PMC text mining. Sharing a sentence is not in itself a finding about the gene and the disease. The quoted sentences say what the papers report.
tumor (1 paper, 2023). "Except for IGLC4, IGLC5, and IGLC7, 4 IGLC (IGLC1, IGLC2, IGLC3, and IGLC6) expressions were positively correlated with infiltration scores of 6 tumor-infiltrating immune cells (B cell, T cell CD4, T cell CD8, neutrophil, macrophage, and DC)." (PMID 37784026, 2023). "The expressions of IGLC5 and IGLC7 had significant difference in different pathologic metastasis (M), one of tumor, node, and metastasis (TNM) staging system, categories of CESC." (PMID 37784026, 2023). "Except for IGLC4, IGLC5, and IGLC7, the expressions of 4 IGLCs were positively correlated with infiltration scores of some tumor-infiltrating immune cells respectively." (PMID 37784026, 2023).